CRP (C-reactive protein)
Diseases named in the same sentence as CRP in open-access papers (continued):
Sharing a sentence is not in itself a finding about the gene and the disease.
coronary artery disease (continued). "Female patients were older, had a shorter disease duration, lower rates of HLA-B27 positivity, higher rates of non-radiographic SpA, higher incidence of peripheral manifestations, less frequent family history of axSpA, lower levels of CRP, and less frequent ischemic heart disease." (PMID 38664785, 2024). "Many studies have demonstrated that CRP might affect coronary artery disease progression by activating the complement pathways and platelets and suppressing fibrinolysis." (PMID 39274304, 2024). "In particular, the ingestion of olive oil phenolic compounds has been associated with a decrease in levels of interleukin-6 (IL-6) and C-reactive protein (CRP) in patients with stable coronary heart disease and it is proposed as a supplementary intervention to the pharmacological agenda." (PMID 39125686, 2024). "Keyword analysis results identified “mendelian randomization,” “inflammation,” “interleukin-6,” “c-reactive protein,” “coronary-heart-disease” as the top 5 most frequently used keywords that reflect current hotspots and prospective future trends in this field of research." (PMID 38579070, 2024). "Despite the fact that CRP has been related to coronary heart disease, ischemic stroke, and cardiovascular mortality, clinical investigations suggest that ischemic vascular events depend considerably on conventional risk factors and other markers of inflammation." (PMID 38673472, 2024). "This is similar to MR findings for coronary heart disease, where IL-6 but not CRP have been shown to play a potential causal role." (PMID 38699368, 2024). "Those with multivessel coronary disease have the highest serum level of CRP." (PMID 38248862, 2024). "This would explain the observed elevation of CRP in AS and coronary disease, while also explaining the repeatedly negative results of MR analyses which aim to evaluate for a causal relationship between elevated CRP and coronary disease." (PMID 37914784, 2023). "Based on the fact that coronary artery disease (CAD) accounts for the highest proportion of CVD mortality (estimated 1 in 4 deaths), we conducted an investigation into the association between CRP and the risk of CAD." (PMID 38074681, 2023). "Furthermore, the authors demonstrated that liraglutide in combination with metformin improved the atherogenic lipid profile and reduced CRP in patients with newly diagnosed T2D and stable coronary artery disease." (PMID 37118678, 2023). "Though the causal association between bilirubin and HF was not supported from MR analysis, it would not devalue the role of bilirubin acting as a prognostic factor for HF, as it goes for the role of C-reactive protein in coronary heart disease and interleukin 1β in Alzheimer’s disease." (PMID 36713081, 2023). "A supplementation with ALA to lower the omega-6/omega-3 ratio may lead to up to a 50% reduction in C-reactive protein (CRP), a risk factor for coronary heart disease." (PMID 37762621, 2023). "Notably, CRP binds to LDL and is present in atherosclerotic plaques, leading to suggestions of its potential causal role in coronary heart disease." (PMID 37686743, 2023). "The GID score consists of five predictors as following: severe coma (Glasgow coma scale score of ≤8, 2 points), histories of cancer or coronary artery disease (1 point for each history), elevated C-reactive protein (CRP) levels (>10 mg/dl, 1 point), and bandemia (>10% band cells, 1 point)." (PMID 36961810, 2023). "As a simple example, genetic predictors of C-reactive protein concentrations in the IL6R region are associated with coronary artery disease risk, but those in the CRP region are not." (PMID 36736292, 2023). "In other studies, p38 inhibitors lowered CRP in ischemic heart disease." (PMID 38203261, 2023). "Moreover, a decrease in C-reactive protein (CRP) was also noticed (a biomarker of inflammation used in the prediction of coronary heart disease), probably via a reduction in LDL-cholesterol levels." (PMID 36429143, 2022).
coronary artery disease (continued). "Furthermore, clinical studies have demonstrated the prognostic role of CRP and serum amyloid A levels in patients with coronary artery disease (CAD)." (PMID 35242789, 2022). "The current commonly used biomarker CRP often shows no further rise in individuals with genetically elevated CRP levels by the increased risk of ischemic heart disease." (PMID 35406670, 2022). "The next 17 top keywords with the strongest citation bursts were: angiotensin converting enzyme 2, inhibition, chloroquine, myocarditis, model, blockade, SARS-CoV, MERS-CoV, c reactive protein, severity, death, coronary artery disease, NF-κB, endothelial cell, cancer, admission, and body mass index." (PMID 36568760, 2022). "In that same study, it has shown that leptin and resistin are linked with coronary artery disease regardless of CRP." (PMID 36299943, 2022). "In our cohort, patients who died during hospitalization had a higher heart failure rate because of ischemic heart disease, a higher heart rate, a lower left ventricular ejection fraction, higher CRP levels, lower albumin levels, and worse renal function than those who were discharged alive." (PMID 37234387, 2022). "In addition to myocardial strain, high-sensitivity CRP (hs-CRP) can predict the presence of significant coronary artery disease." (PMID 35621834, 2022). "The patients who died had a significantly higher prevalence of ischemic heart disease; a higher heart rate; higher levels of plasma C-reactive protein, blood urea nitrogen (BUN), and creatinine; a lower serum albumin level; and a lower estimated glomerular filtration rate than surviving patients." (PMID 37234387, 2022). "Prognostic factors of coronary heart disease have been discussed in the literature, including gender, age, smoking status, diabetes mellitus, systemic hypertension, hypercholesterolemia, high sensitivity C reactive protein (hs-CRP), and body mass index (BMI)." (PMID 35069785, 2022). "The inflammatory mediators C-reactive protein and interferon-gamma were found to enhance the expression of macrophage tissue factor levels that may contribute to the hypercoagulable state in coronary disease." (PMID 35268431, 2022). "Moreover, a reduction in IL-6, CRP and a significantly lower incidence of recurrent cardiovascular events in patients with coronary artery disease (CAD) with persistent inflammatory states were reported in CANTOS." (PMID 36142625, 2022). "It has been shown that α-linolenic acid [18:3(n-3)], extracted from nut is inversely associated with interleukin-6 (IL-6), soluble tumor necrosis factor (TNF) receptors 1 and 2, fibrinogen, and C-reactive protein (CRP) levels in both healthy subjects and individuals with coronary artery disease." (PMID 35425791, 2022). "Recent clinical studies indicate that there is a significant independent association between pre-procedural CRP levels and the occurrence of CA-AKI in patients with stable coronary artery disease undergoing elective PCI and in those with ST-segment elevation MI undergoing primary PCI." (PMID 34297744, 2021). "The multivariate analysis revealed that after adjustment for age, ischemic heart disease, chronic kidney disease, SpO2 during oxygen therapy and CRP when administering HFNO, the predictive value of death and ineffectiveness of HFNO therapy was high—AUC 0.851 and 0.800, respectively." (PMID 34682874, 2021). "Based on their differential expression in the RAA tissue of patients with or without IHD, we present here a specific set of IHD-associated RNAs expressing significantly differently when compared to coronary artery disease complexity, and correlating with CRP, NT-proBNP, and surgery outcomes." (PMID 34926599, 2021).
coronary artery disease (continued). "Women with premature menopause were more likely to be current or former smokers; had higher BMI; had greater prevalence of atherosclerotic risk factors and coronary artery disease (CAD), chronic obstructive pulmonary disease (COPD), and venous thromboembolism; and had higher C-reactive protein." (PMID 33690615, 2021). "The LASSO selection identified 6 variables (age, history of coronary heart disease, CRP, AST, D-dimer, and neutrophil/lymphocyte ratio) and resulted in the best performing score with an area under the curve of 0.79 in the derivation cohort and 0.80 in the validation cohort." (PMID 33620680, 2021). "A vegan diet, compared to the American Heart Association (Dallas, TX, USA) diet for coronary heart disease (CHD), resulted in similar reductions in BMI, waist circumference, markers of glycemic control, blood lipids, and a 32% lower high-sensitivity C-reactive protein (a pro-inflammatory marker)." (PMID 34836399, 2021). "The LASSO selection identified 6 variables that predicted severe outcome: age older than 50 years, history of coronary heart disease, CRP levels greater than 2.0 mg/dL, AST greater than 35 U/L, D-dimer equal to or greater than 917 μg/L, and neutrophil/lymphocyte ratio greater than 3.3." (PMID 33620680, 2021). "A previous MR study indicated that CRP concentration itself was unlikely to be even a modest causal factor in coronary heart disease." (PMID 33613636, 2021). "LASSO and multivariate data analysis-based prediction models showed that higher age, coronary heart disease (CHD), percentage of lymphocytes (LYM%), procalcitonin (PCT), urea, CRP, and D-dimer (DD) could be potential risk factors for mortality of COVID." (PMID 34496940, 2021). "The participants with lower activity of GPx3 was more likely to be older (p = .009) and to have higher mean CIMT (p = .004) and hs‐CRP (p = .012) levels, as well as to have the history of smoking (p = .025), previous coronary heart disease (p = .042), and carotid plaque (p = .049)." (PMID 32862561, 2020). "Consequently, “classic” inflammatory biomarkers like CRP and interleukins have been already evaluated in the setting of coronary heart disease." (PMID 32093244, 2020). "In addition, confounding effects of smoking in the association between coffee and CRP level are possible as previously reported for coronary artery disease or CVD mortality, which were closely linked to CRP levels." (PMID 32397288, 2020). "In contrast, Mendelian randomization tests of causality suggest no causal association of CRP with coronary heart disease." (PMID 33033455, 2020). "In a cohort of 981 patients with coronary heart disease enrolled in the Heart and Soul study, HCV seropositivity was associated with changes in levels of CRP, TNF‐α, IL‐6 increased Framingham risk scores, and hospitalizations due to clinical cardiac failure and death." (PMID 31785111, 2020). "However, studies on CAD population have found that hs-CRP level is positively correlated with the severity of coronary artery disease." (PMID 33028234, 2020). "Consequently, previous investigations focused on the association between CRP and/or high-sensitive CRP (CRP assessed by a more sensitive assay to estimate the risk of CAD) and ventricular arrhythmias related to ischemic heart disease or/and ischemic HF." (PMID 32093244, 2020). "Older age (OR 1.1, 95% CI 1.05–1.1, P=0.005), ischemic heart disease (OR 2, 95% CI 1.1–3.7, P=0.0197), higher creatinine level (OR 2.3, 95% CI 1.3–4, P=0.0043), and elevated CRP level and CRP-to-albumin ratio (OR 1.1, 95% CI 1.01–1.02, P < 0.0001; OR 1.1, 95% CI 1.02–1.03, P < 0.0001, respectively)." (PMID 31828049, 2019). "CRP is a non-specific inflammatory marker that has long been recognized as associated with various inflammatory diseases including coronary artery disease and cancer." (PMID 30662766, 2019).
coronary artery disease (continued). "ESR and CRP are well-known surrogate markers of inflammation that reflect activity of various disease states such as infection, malignancy, connective tissue disease, and coronary artery disease." (PMID 31891116, 2019). "Our results may provide a strong basis for studying the role of CRP and miRNAs in ischemic heart disease." (PMID 31063484, 2019). "With the aggravation of the severity of the coronary artery disease, the serum CP-IgA, hs-CRP and IL-6 levels gradually increased in patients with CHD, all were significantly higher, when compared to those in the control group, and the differences were statistically significant (P = 0.000)." (PMID 31088358, 2019). "In fact, CRP also plays a significant role in coronary heart disease." (PMID 31208420, 2019). "Our results may provide a strong basis for research on the relation between CRP and miRNAs and their role in ischemic heart disease and subsequent reperfusion therapy." (PMID 31063484, 2019). "HMGB1 levels are positively correlated with CRP levels in coronary artery disease patients." (PMID 30501043, 2018). "Similarly, a large meta-analysis of population-based studies of coronary heart disease has found that values for CRP are sufficiently stable over time." (PMID 29140226, 2018). "For example, a-linolenic acid (18:3(n-3)), extracted from a specific nut was inversely associated with CRP, IL-6, soluble tumor necrosis factor (TNF) receptors 1 and 2 and fibrinogen levels in healthy individuals and/or patients with stable coronary artery disease." (PMID 30131846, 2018). "Other studies on persons without IBD concluded that systemic inflammation based on serum C-reactive protein (CRP) level predicts ischemic heart disease, cerebrovascular disease, and cardiovascular death, even after adjustment for the traditional cardiovascular risk factors." (PMID 30169521, 2018). "Therefore, further studies are needed to assess the true impact of leukocytosis in coronary heart disease, compare it with other inflammatory markers such as CRP, and promote its use in predicting coronary heart disease." (PMID 28753607, 2017). "In this type of analysis, several authors have argued against a causal association of CRP with coronary heart disease due to the lack of consistency between the effect of CRP genetic variants on CVD and CRP levels." (PMID 28250574, 2017). "A recent meta-analysis of studies investigating single nucleotide polymorphisms (SNPs) hypothesized a causal role of the IL6R-gene signalling via the inflammatory markers CRP and fibrinogen in the development of coronary heart disease (CHD)." (PMID 27495156, 2016). "Moreover, hs-TnT levels in diabetic subjects were recently described as the strongest predictor (in addition to sST2 and hs-CRP) of short-term outcome in patients with stable coronary artery disease." (PMID 27809845, 2016). "It has been suggested that consumption of VOO during 3 weeks leads to a decrease of IL6 and C-reactive protein (CRP) higher than the decrease observed after refined OO consumption in patients with stable coronary heart disease, indicating an important role of minor antioxidant compounds of EVOO." (PMID 26840281, 2016). "A meta-analysis reported that CRP concentrations have continuous associations with coronary heart disease, ischaemic stroke and vascular as well as non-vascular mortality." (PMID 27658041, 2016). "Acute exercise induces a transient inflammatory response through the increase in several cytokines such as interleukin-6, tumor necrosis factor-α, C-reactive protein, and nuclear factor kappa B and oxidative stress in healthy subjects and in subjects with coronary artery disease." (PMID 26557715, 2015). "High levels of IL-6 and CRP predicted incident coronary heart disease." (PMID 25722960, 2015). "Furthermore, plasma C-Reactive protein (CRP) and lipoprotein-associated phospholipase A2 (Lp-PLA2) activity were independent predictors of coronary heart disease." (PMID 26386597, 2015).
coronary artery disease (continued). "We identified EN-RAGE as a novel biomarker for incidence of coronary heart disease, independent of established risk factors and inflammatory markers, such as C-reactive protein." (PMID 26386597, 2015). "Take together, more pronounced traditional risk factors and a higher level of CRP in RA, compared to IBD, may contribute to the different associations with ischemic heart disease and cardiovascular mortality between RA and IBD, reported in literature." (PMID 25337037, 2014). "CRP binds to LDL and is present in atherosclerotic plaques, so it has been proposed that CRP may have a causal role in coronary heart disease." (PMID 24587807, 2014). "It has been reported that elevated levels of inflammation biomarkers, especially that of C-reactive protein (CRP) and interleukin-6 (IL-6), are inversely associated with various HRV indices in apparently normal adults and in patients with coronary heart disease (CHD)." (PMID 24722336, 2014). "The hs-CRP value can also be used as an independent predictor of coronary heart disease." (PMID 24684833, 2014). "In addition, the association of several significant SNPs in our study with asthma, C-reactive protein levels and coronary heart disease highlights the relationship between the inflammatory response and these disorders." (PMID 25340798, 2014). "Asian populations seem to have low levels of CRP, which may reflect their low prevalence of coronary heart disease in comparison with those of Western populations." (PMID 24587705, 2014). "In a case control study of 100 patients with established coronary artery disease (CAD), plasma protein-bound nitrotyrosine levels were found to be significantly higher among patients with CAD even after adjustment for traditional risk factors for CVD and CRP." (PMID 24251116, 2013). "Atorvastatin lowers the risk factors for coronary artery disease by not only reducing total LDL cholesterol levels but also by reducing circulating levels of electronegative L5 LDL, thereby impeding L5-induced endothelial CRP and ROS production." (PMID 23950953, 2013). "Genetic variations and haplotypes in the CRP gene are associated with differences in plasma CRP levels but not with the risk of coronary heart disease." (PMID 23894396, 2013). "This suggests that CRP levels in plasma are not causally related to coronary heart disease despite their prospective association to risk of CHD in prospective studies." (PMID 23894396, 2013). "The risk score for coronary heart disease was associated with increased levels of CRP, but not with any polymorphism or haplotype." (PMID 23049543, 2012). "Also, Pai and colleagues examined the plasma levels of IL-6, CRP and tumor necrosis factor (TNF)-alpha as markers of risk for coronary artery disease among people who were free of cardiovascular disease at baseline." (PMID 22708908, 2012). "Also, it has been shown that levels of C-reactive protein (CRP), IL-6, and TNF-α were higher in patients with coronary artery disease (CAD) and were linked to an increased risk of adverse cardiac events and mortality." (PMID 22830072, 2012). "Several studies have established that CRP serum levels and other inflammatory markers (cytokines such as IL-1, IL-6, and TNF-α) are risk factors for coronary disease, although their levels are elevated in both coronary disease and chronic infections." (PMID 28348657, 2011). "In the LURIC Study cohort the A-allele of rs2259816 is associated with decreased CRP but not with coronary artery disease." (PMID 21062467, 2010). "Multiple types of reporting bias, and publication bias, make the magnitude of any independent association between CRP and prognosis among patients with stable coronary disease sufficiently uncertain that no clinical practice recommendations can be made." (PMID 20532236, 2010).